CXCR3 (C-X-C motif chemokine receptor 3)
Diseases named in the same sentence as CXCR3 in open-access papers (continued):
Sharing a sentence is not in itself a finding about the gene and the disease.
influenza (continued). "The majority of Tet+ cTfh cells expressed CXCR3, consistent with the ‘Th1’ skew in the total CD4+ T cell and cTfh cell response to influenza vaccination." (PMID 34726156, 2021). "Of note, among influenza- and citrulline-specific cells as well as in the general CD4 population around half of the CXCR3+ cells also expressed CXCR5 and to a lesser extent CCR6 (data not shown)." (PMID 32423478, 2020). "During influenza infection, secretion of CXCL9 and CXCL10 from the inflamed epithelium recruits CD8 T cells expressing CXCR3 chemokine receptors." (PMID 32817719, 2020). "In these studies, the reduced efficacy was due to lower CXCR3 expression on the CD4+ T cells, which led to reduced accumulation of these cells in the influenza infected lung." (PMID 33373420, 2020). "Neutrophils isolated from influenza-infected mouse lungs were stimulated with CCR1, CCR5, CXCR2, and CXCR3 specific ligands CCL3, CCL4, IL-8, and CXCL11 (100 ng/mL), respectively, and incubated for 4 h." (PMID 31041196, 2019). "CXCR3-biased cTfh cells play an important role in nAb production in HIV-1 controllers and following influenza vaccination." (PMID 31300682, 2019). "Activation of CXCR3+ CCR6- cTFH is observed in response to both novel and recall antigenic challenges, as suggested by their activation after both influenza vaccine and HBV." (PMID 30303980, 2018). "It has been reported that the frequency of CXCR3+ Tfh1-like cells increased, while it decreased for CCR6+ Tfh17-like cells at D7 post-influenza vaccination." (PMID 26333070, 2015). "Likewise, infection with either SARS-CoV-2 or influenza, led to an expansion of CCR6+CXCR3− bystander memory B cells (MBCs) alongside the CCR6+CXCR3+ virus-specific MBCs in the lungs of the infected animals." (PMID 41149075, 2025). "Similarly, in an influenza infection model, alcohol-fed mice exhibited decreased homing to lungs, reduced CD69, CD103, and CXCR3 positive tissue resident CD8+ T cells." (PMID 37485352, 2023). "A nonadjuvanted trivalent split seasonal influenza vaccine up-regulated the frequency of CXCR3+ cell." (PMID 37853288, 2023). "cTfh cells share phenotypic and functional properties to GC Tfh cells, and it has been shown that inactivated influenza vaccination (IIV) induces expansion and PD-1/ICOS-activation of CD4+CXCR5+CXCR3+ cTfh type-1 (cTfh1) cells, which correlated with antibody and CD19+CD27++CD38++ ASC responses." (PMID 33976217, 2021). "CXCR3+ and CCR5+ NK cells migrate to the lungs during influenza infection." (PMID 32974217, 2020). "In contrast to this we found only a few influenza-specific cells co-expressing several chemokine receptors, these were mostly CXCR3+ cells carrying CCR6 and/or CXCR5 (data not shown)." (PMID 32423478, 2020). "Similarly, we examined the surface expression of the chemokine receptors CCR6, CXCR3 and CXCR5 and found a general decrease in the frequency of CXCR5+ cells for all autoreactive as well as the influenza-specific T cells at follow-up." (PMID 32423478, 2020). "Neutrophils isolated from influenza-infected mouse lungs were stimulated with CCR1, CCR5, CXCR2, and CXCR3 specific ligands including CCL3, CCL4, IL-8, and CXCL11 (100 ng/mL) for 20 min, followed by incubation with a 1:10 ratio of Streptococcus pneumoniae (serotype 3) for 90 min." (PMID 31041196, 2019). "In contrast to what was observed in the UK unadjuvanted influenza vaccination cohort, there was no significant change in the CXCR3 or CCR6 transcripts, indicating that the Th1/2/17 phenotype of these cTfh cells is not skewed by either adjuvant." (PMID 31175140, 2019). "The administration of trivalent split-virus influenza vaccines was shown to induce the temporary accumulation of circulating ICOS+ CXCR3+ CXCR5+ CD4+ T cells, and up to 60% of these cells were specific for influenza antigens and correlated with an increase in preexisting antibody titers." (PMID 31300682, 2019).
influenza (continued). "Interestingly, we observed that seasonal influenza vaccination elicited median increases in PD-1 MFI on both CCR7- and CCR7+ subsets, specifically in CXCR3+CCR6- cTFH, and the magnitude of increase was greater within the CCR7- subset." (PMID 30303980, 2018). "In contrast to Treg cells from naïve SPF mice, human CD4+CD127lowCD25+ Treg cells in peripheral blood already express a substantial amount of CXCR3 at steady state and influenza vaccination did not induce significant changes in their frequency." (PMID 29951069, 2018). "cTFH that express CXCR3 but not CCR6 transiently increase 7 days following influenza vaccination, are antigen-specific, upregulate expression of ICOS and PD-1, and correlate with both serological response and the day 7 peak in PB." (PMID 30303980, 2018). "Since CXCR3+ Tfh1 cells have been shown to be inferior to CXCR3− Tfh2/17 cells at providing help to naïve B cells, it was suggested that an influenza vaccine inducing Tfh2/17 cells rather than Tfh1 cells would be preferable." (PMID 29181005, 2017). "Extensive surface phenotyping was performed together with combinatorial tetramer staining to measure the frequency, memory status (CD45RA and CCR7), chemokine receptor expression (CXCR3, CCR4, CCR6 and CXCR5) as well as activation status (CD38) of these influenza-specific T cells." (PMID 27571776, 2016). "In HIV seronegative individuals, the emergence of blood ICOS+CXCR5+CXCR3+ TFH that are able to produce IL-21 correlated with influenza-specific B cell responses and blood ICOS+IL-21+ influenza-specific TFH expand after immunization and correlate to antibody responses." (PMID 28082992, 2016). "However, only CTL memory induced by intranasal vaccination was protective against influenza viral challenge, and correlated with an enhancement of memory CTLs in the airways and CD103+ CD69+ CXCR3+ resident memory-like CTLs in the lungs." (PMID 27997610, 2016). "In general, CXCR5, compared to CXCR3 and CCR6, is the chemokine receptor that was most prominently expressed on tetramer-positive cells with mean levels of up to 40% for citrulline-specific and 54% for influenza-specific populations while for the general CD4+ population it was only around 10%." (PMID 32423478, 2020). "Influenza challenge results in a strongly polarised type-1 response with production of interferon (IFN)-γ and dominance of CXCR3-expressing CD4+ and CD8+ T cells, with no other polarised T-cell response observed." (PMID 37696824, 2023). "Two prior studies evaluated mRNA vaccination for influenza in humans and non-human primates and found robust induction of ICOS+CXCR3+PD-1+ cTfh responses and neutralizing antibodies." (PMID 34874183, 2022). "Lung-recruited neutrophils induced CCR1, CCR2, CCR3, CCR5, CXCR1, CXCR3, CXCR4, which were absent or marginally induced in peripheral blood neutrophils from influenza-infected mice." (PMID 31041196, 2019). "Thus, decreased level of CXCR3 on NK cells fails to explain their enhanced responses during pregnancy but could represent a mechanism of protection to avoid an excessive recruitment of CD56bright NK cells to the lung of influenza-infected pregnant women and to restrain lung damage." (PMID 31708922, 2019).
vitiligo (46 papers, 2017 to 2025). Generalized well circumscribed patches of leukoderma that are generally distributed over symmetric body locations and is due to autoimmune destruction of melanocytes. "CXCL10 is raised both in the skin and serum of vitiligo patients, and CXCR3, its receptor, is expressed on pathogenic T cells." (PMID 39201060, 2024). "CXCR3 has long been viewed as a promising therapeutic target in vitiligo, given its key role in disease progression." (PMID 41007740, 2025). "Functional CD8+ TRMs have been identified in both active and stable vitiligo, with CXCR3 expression found in most of these cells." (PMID 41007740, 2025). "It was found that CXCR3-depleting antibodies can reverse vitiligo by reducing autoreactive T cell numbers." (PMID 39201060, 2024). "Nonetheless, increased CXCL4 levels would be consistent with an upregulated CXCR3 signaling in vitiligo." (PMID 38715599, 2024). "CD8+ Trm cell subpopulations expressing CD69, CD103, and CXCR3 were enriched in the epidermal compartments of patients with vitiligo, and they were significantly enriched in stable and active lesions." (PMID 38779662, 2024). "In VDLR, activated CD8+CXCR3+ T-cells are observed in the vitiligo-like infiltrate of anti-PD-1 recipients." (PMID 36776862, 2023). "Similar to vitiligo, analysis of skin samples from psoriasis patients shows that CXCR3 is vital for CD8 T cell trafficking to the affected dermis and then into the epidermis in psoriasis plaques." (PMID 36675078, 2023). "Therapies that disrupt the pathway targeting IFN-γ, the IFN-γ receptor, the downstream signal JAK-STAT pathway, CXCL10 and its receptor CXCR3 are the most promising in vitiligo management." (PMID 37298700, 2023). "Together, T-96 decreased CXCR3 expression on CD8+ T cells from patients with vitiligo and blocked the chemotactic migration of CXCR3+CD8+ T cells under the CXCL9 and CXCL10 derived from inflamed keratinocytes." (PMID 37403086, 2023). "Recently, the importance of the Th1-type immune response in the pathogenesis of vitiligo, as well as the C-X-C Motif Receptor 3 (CXCR3) and its corresponding chemokine, CXCL10, was highlighted." (PMID 36556267, 2022). "Targeting CXCR3 with depleting antibodies in a mouse model reduced the number of self-reactive T cells and reversed vitiligo manifestations." (PMID 36439174, 2022). "We demonstrate that stress keratinocytes communicate with adaptive immune cells via the CXCL9/CXCL10/CXCR3 axis to create local inflammatory loops that are active in stable vitiligo." (PMID 35653192, 2022). "On the other hand, inhibition of CXCR3 was reported to prevent the CXCL10-induced melanocyte apoptosis and T cell infiltration in the skin, and blocking their receptor CXCR3 by CXCR3 antibodies led to repigmentation in mice with established vitiligo." (PMID 35096274, 2022). "Melanocyte-specific autoreactive T cells in patients with vitiligo express CXCR3 in both the blood and in lesional skin." (PMID 34970551, 2021). "There were higher percentages of CXCR3(+) CD8(+) T cells in vitiligo patients compared with controls, while the expression of CXCR3(+) CD4(+) T cells also increased in patients with progressive vitiligo." (PMID 33679890, 2021). "In a mouse model, CXCR3-depleting antibodies reduce autoreactive T-cell numbers and reverses vitiligo." (PMID 34970551, 2021). "It is interesting that the circulating CXCR3+ CD8+ TRCM cells in vitiligo patients show increased proliferation potential compared to the cells in healthy people." (PMID 32443482, 2020). "These include CXCL9, CXCL10, and CXCL11 and its receptor CXCR3, both in peripheral cells of the immune system and in the skin of patients diagnosed with vitiligo." (PMID 32992956, 2020). "Specifically, the in vivo assay conducted in a mouse vitiligo model verified that, mice received Cxcr3-/- T cells develop minimal depigmentation, as do mice lacking Cxcl10 or treated with CXCL10-neutralizing antibody." (PMID 32532953, 2020).
vitiligo (continued). "It has been previously shown that skin memory T regulatory cells express CXCR3, that these cells are expressed in vitiligo skin during the depigmenting process and they remain in the skin even after repigmentation." (PMID 31097717, 2019). "Expression of CXCR3 was found on the majority of CD8+ TRM cells in human vitiligo, including melanocyte‐specific cells, and these TRM cells were poised for the secretion of IFN‐γ and TNF‐α." (PMID 31230406, 2019). "Targeting total CXCR3 by using depleting antibodies has provided encouraging results in vitiligo mouse model." (PMID 31097717, 2019). "Melanocytes of vitiligo patients have strong basal expression of chemokine-receptor-3 (CXCR3) isoform B which is directly regulated by IFNγ." (PMID 31097717, 2019). "We show that CXCL10-induced apoptosis occurs to a greater extent in melanocytes extracted from vitiligo patients and that this apoptosis can be prevented by using CXCR3 antagonists, by silencing CXCR3B, or by using caspase-inhibitors." (PMID 31097717, 2019). "Chemokine (C-X-C motif) receptor 3 (CXCR3) is the main receptor for these chemokines and it has been reported to be increased in vitiligo patients." (PMID 31097717, 2019). "Patients receiving anti-PD-1 antibody therapy for metastatic tumor can also develop vitiligo-like skin lesions with infiltration of CXCR3-expressing CD8 T cells." (PMID 30320116, 2018). "Similarly, TRM cells work as a contributing factor in the recurrence of vitiligo and CXCR3, which is the homing receptor of CD8+ TRM cells, exhibited heightened expression." (PMID 40468464, 2025). "Recent studies have reported that the maintenance of decolorization of skin lesions in patients with vitiligo is simultaneously associated with autoreactive recirculating memory T (TRCM) cells in the blood, which bind to CXCR3 on the surface of TRCM cells via CXCL9 and CXCL10." (PMID 38779662, 2024). "Higher CXCL4 levels would be in line with the increased CXCR3 signaling found in vitiligo." (PMID 36911664, 2023). "Therapies that disrupt the pathway targeting IFN-γ, the IFN-γ receptor, the downstream signal JAK-STAT pathway, CXCL10 and its receptor CXCR3 have been some of the most promising in vitiligo management and may become the first to be approved." (PMID 37298700, 2023). "CXCR3 expression is elevated in vitiligo melanocytes compared to healthy pigment cells." (PMID 36911664, 2023). "In addition, the IFNγ-CXCR3 pathway has been determined to be critical to the migration of autoreactive CD8+ T cells in vitiligo in mice and humans, and correlates with disease progression and severity." (PMID 34012438, 2021). "The results could contribute to the future design of new specific antagonists in the therapy of vitiligo and other pathologies in which the CXCR3 axis is involved." (PMID 32992956, 2020). "Depleting antibodies directed against CXCR3 were also able to reverse vitiligo in a mouse model." (PMID 30320116, 2018). "Indeed, the tissue-resident memory T (Trm) cells in vitiligo skin express CXCR3, the receptor for CXCL10, and are prone to IFN-γ production." (PMID 30515176, 2018). "Highly induced CXCL10 and CXCR3 were found in vitiligo patients." (PMID 29456788, 2017). "Moreover, CXCR3 may contribute to vitiligo relapses, as depigmentation frequently recurs at previously affected sites, suggesting the role of resident memory T cells (TRMs)." (PMID 41007740, 2025). "Although these results are preliminary, they may provide justification for further studies in targeting CXCR3 in vitiligo, which proposes the use of a depleting Ab to create a greater clinical efficacy by removing autoreactive cells rather than modulating their migration phenotype." (PMID 36119071, 2022). "As a consequence of antagonizing CXCR3, a reduction of the chemotaxis of the cells of the immune system could prevent the appearance of new lesions and the progression of existing lesions in vitiligo patients." (PMID 32992956, 2020).
vitiligo (continued). "Emerging therapeutic approaches for vitiligo are under investigation and target multiple immune pathways, including IFN-γ inhibitors, CXCL10/CXCR3 antagonists, Janus kinase (JAK) inhibitors, PD-1/PD-L1 modulation, and HSP70i DNA-based therapies." (PMID 40861456, 2025). "Gene expression analysis of vitiligo lesions showed that interferon-γ (IFN-γ) and IFN-γ-induced genes, including T-cell chemokine receptor CXCR3 and its multiple ligands, such as CXCL9 and CXCL10 were significantly upregulated." (PMID 37207234, 2023). "In lesional skin and serum from vitiligo patients, the gene expressions of CXCL10 and CXCR3 are significantly upregulated." (PMID 36675078, 2023). "Most studies on vitiligo have focused on active disease, and the importance of the CXCL9/CXCL10/CXCR3 axis is well established from studies on human skin samples." (PMID 35653192, 2022). "Compared with the patients with stable vitiligo, the patients with progressive disease had higher frequencies of both CXCR3+ CD8+ and CXCR3+ CD4+ T cells, suggesting a potential indicative role of CXCR3 in disease activity." (PMID 35096274, 2022). "Multiple monoclonal antibodies are available for vitiligo treatment, targeting IFN-γ, CXCL10, CXCR3, HSP70i, IL-15, IL-17/23, and TNF." (PMID 36119071, 2022). "Keratinocytes secrete CXCL9 and CXCL10 to attract and activate CXCR3+CD8+ T cells, and these chemokines are present in the blister fluid of human vitiligo patients." (PMID 35653192, 2022). "Gene expression analysis of both human vitiligo skin and vitiligo mouse model skin revealed the upregulation of IFN-γ-specific signature, including chemokines CXCL10 and CXCL9, and their receptor CXCR3, which is expressed on T cells." (PMID 35432377, 2022). "In patients with vitiligo, the overexpression of chemokine receptors of the CXC family has been reported, namely CXCR3 and CXCR6, as well as the chemokines CXCL9, 10, and 11, natural ligands of CXCR3, and CXCL16, the only known natural ligand of CXCR6." (PMID 32992956, 2020). "In the case of the CXCR3 axis, the overexpression of the CXCR3 receptor in CD8+ and memory T lymphocytes in the skin and peripheral blood of patients with vitiligo has been reported." (PMID 32992956, 2020). "This matches with the observation of enriched CXCR3+, CD8 resident memory T cells in vitiligo patients." (PMID 30320116, 2018). "Segmental vitiligo also exhibits an innate immune component and increased C-X-C Motif Chemokine Receptor 3 (CXCR3)B mRNA expression both in lesional and non-lesional skin." (PMID 39274437, 2024). "Additionally, the researchers revealed that the activated IFNγ-responsive fibroblasts can recruit CXCR3+ T cells and interact with melanocytes by secreting chemokines CXCL9/CXCL10 in vitiligo lesions." (PMID 37809065, 2023). "In vitiligo skin and peripheral blood mononuclear cells (PBMC) from patients with vitiligo and mouse models of vitiligo, activated CD8+ T cells express the chemokine receptor CXCR3." (PMID 37403086, 2023). "CD8+ T lymphocyte toxicity is also an important component of vitiligo pathogenesis, therefore therapies blocking IFN-γ, the IFN-γ receptor, the ligands CXCL10 and CXCL9 and the receptor CXCR3 may also be worth exploring and testing in clinical studies." (PMID 37298700, 2023). "However, the levels of IFNG, PRF1, GZMB and CXCR3, CXCL9, CXCL10, CXCL12, and other cytokines also had an upward trend in the vitiligo group." (PMID 37207234, 2023). "Research is in progress to investigate the important cytokines involved in the pathogenesis of vitiligo, including IFN-γ, CXCL10, CXCR3, HSP70i, IL-15, IL-17/23, and TNF, the blockade of which has undergone preliminary attempts in animal models and some patients." (PMID 36119071, 2022). "Furthermore, serum CXCL10 levels were associated with the Vitiligo Area Scoring Index (VASI) of patients with progressive vitiligo, suggesting that the CXCL10/CXCR3 axis mediates T cell recruitment into the skin of progressive vitiligo." (PMID 34371735, 2021).